CYP21A2 (cytochrome P450 family 21 subfamily A member 2)
Diseases named in the same sentence as CYP21A2 in open-access papers (continued):
Sharing a sentence is not in itself a finding about the gene and the disease.
hyperandrogenism (18 papers, 2007 to 2025). Excessive secretion of androgens from the adrenal glands or gonads. "We recommend screening for NCAH due to 21-hydroxylase (CYP21A2) deficiency in adolescents and adult women who present signs and symptoms of hyperandrogenism (Level of Evidence A)." (PMID 39678099, 2024). "Up to 95% cases of CAH are due to mutations in CYP21A2 gene and subsequent 21α-hydroxylase deficiency, characterized by impaired cortisol synthesis and adrenal androgen excess." (PMID 32610579, 2020). "It is reported that CYP21A2 mutations increase the risk of hyperandrogenism, especially in carriers of p.Val281Leu than carriers of severe mutations." (PMID 32714392, 2020). "Heterozygosity for CYP21A2 mutations in females is possibly related to increased risk of developing clinical hyperandrogenism." (PMID 28487735, 2017). "CYP21A2 mutation heterozygote carriers seem to have an increased risk of hyperandrogenism." (PMID 35289513, 2022). "In conclusion, females with hyperandrogenism are likely to bear heterozygous CYP21A2 mutations." (PMID 28487735, 2017). "Heterozygous CYP21A2 carriers seldom manifest clinically relevant psychoneuro-social issues, and targeted interventions are rarely necessary unless overt hyperandrogenism is present." (PMID 41387661, 2025). "Women with hyperandrogenism are more frequently identified as heterozygous gene carriers for a non-classic CYP21A2 mutation than in the general population, but to date, there is no precise explanation for the symptoms described in the heterozygous patients." (PMID 32647925, 2020). "This form is caused by CYP21A2 variants that impair the synthesis of 11-deoxycortisol and deoxycorticosterone (DOC), with a resulting lack of cortisol and aldosterone secretion and the accumulation of 17-OH-progesterone (17-OH-P) and progesterone, respectively, producing hyperandrogenism." (PMID 36294476, 2022). "Concurrent screening of the CYP21A2 3′UTR in 150 control females with no hyperandrogenism and no detected mutations in the CYP21A2 gene identified the combination of 3′UTR variants ∗52C>T, ∗440C>T, and ∗443T>C in 12/150 (8%) and ∗12C>T and ∗52C>T in 8/150 (5.3%)." (PMID 28487735, 2017). "Four male individuals who were found to have two variants in CYP21A2 and whose genotypes suggested a potential diagnosis of non-classic CAH (characterised in males by mild signs of hyperandrogenism) were excluded from the secondary findings group." (PMID 40565563, 2025).
Adrenal insufficiency (8 papers, 2007 to 2024). Insufficient production of steroid hormones (primarily cortisol) by the adrenal glands. "Since CAH due to 21-OHD accounts for 95% of all CAH cases, CYP21A2 should be the first gene to investigate in males and virilized girls with adrenal insufficiency." (PMID 35422767, 2022). "The weak inhibition of CYP21A2 by oteseconazole and lack of effect on 3β-HSD2 suggest a negligible risk of adrenal insufficiency and hyperplasia via this mechanism." (PMID 39175536, 2024). "Autoantibodies against steroid 21-hydroxylase (CYP21A2), steroid 17α-hydroxylase (CYP17A1), and cytochrome P450 family 11 subfamily A member 1 (CYP11A1) have been detected in many APS-1 patients with Addison’s disease years before adrenal insufficiency became clinically apparent." (PMID 30002654, 2018).
hyperandrogenemia (8 papers, 2011 to 2024). "RCCX copy number variation haplotypes in 46 individuals with hyperandrogenemia all found to carry the p.Gln319Ter pathogenic variant in the CYP21A2 gene." (PMID 37324257, 2023). "In other studies, higher levels of mean stimulated 17OHP in the carriers of CYP21A2 mutation presented with premature pubarche and late-onset hyperandrogenemia." (PMID 34684072, 2021). "In the present work, our aim was to determine the prevalence of NCAH presenting as premature pubarche (PP), hirsutism, or polycystic ovarian syndrome (PCOS) and to evaluate the molecular spectrum of CYP21A2 mutations in NCAH patients." (PMID 24778650, 2014). "In general, female individuals with the non-classic form carry in compound heterozygosity two mild CYP21A2 pathogenic variants and present symptoms of hyperandrogenemia, hirsutism, premature puberty in early life and or infertility later on in life." (PMID 38637882, 2024). "This suggests that compounds based on curcuminoids may be better and safer inhibitors for use in hyperandrogenic states like polycystic ovary syndrome, especially in children and young adults, and avoid the toxic effects of abiraterone which severely inhibits CYP21A2 activity." (PMID 31533365, 2019). "In the course of Sanger sequencing for the CYP21A2 gene downstream of the TNXB gene, the 46 patients with hyperandrogenemia were previously identified by our group as carriers for the p.Gln319Ter pathogenic variant." (PMID 37324257, 2023). "All 46 samples from the unrelated patients with hyperandrogenemia were further re-analyzed using the commercial real-time PCR CAH Real Fast CNV Assay (Vienna Lab) so as to re-confirm the presence or absence of the duplicated CYP21A2 genes obtained by MLPA." (PMID 37324257, 2023).
Hirsutism (7 papers, 2014 to 2024). Abnormally increased hair growth referring to a male pattern of body hair (androgenic hair). "Premature pubarche and hirsutism, for example, are associated with different percentages of both severe and mild CYP21A2 mutations." (PMID 33666875, 2021). "We assayed stimulated ACTH levels in patients presenting with PP, hirsutism, or PCOS and evaluated the molecular pattern of CYP21A2 gene mutations in such patients." (PMID 24778650, 2014). "Among the 45 adolescent and adult CYP21A2 heterozygote female patients, the most common presenting symptom was irregular menses with or without multicystic ovaries on the ultrasound (32/45), followed by hirsutism in 21/45." (PMID 28487735, 2017). "In subjects with sudden development of hirsutism in adolescents and adults, and high concentrations of testosterone and androstenedione, an additional ACTH stimulation test with determination of 17-OHP together with CYP21A2 genotyping is requested." (PMID 31632355, 2019).
Addison's disease (6 papers, 2014 to 2026). "The most common cause of primary adrenal failure (Addison’s disease) in the Western world is autoimmunity characterized by autoantibodies against the steroidogenic enzyme 21-hydroxylase (CYP21A2, 21OH)." (PMID 34665570, 2021). "The primary autoantigen in Addison's disease is encoded by CYP21A2, which resides within a segmentally duplicated region and is a known locus of germ-line gene conversion." (PMID 24988487, 2014).
autoimmune Addison disease (4 papers, 2007 to 2025). "In autoimmune AD (often termed autoimmune Addison disease, AAD), a consistent serological hallmark is the presence of 21-hydroxylase (CYP21A2) autoantibodies, detectable in ~85% of patients near diagnosis." (PMID 41465179, 2025). "The CYP21A2 variants IVS2-13A/C (rs6467) and rs6474 G>A have been studied only among patients with autoimmune Addison disease (AAD) and acne." (PMID 39062101, 2024).
Ehlers-Danlos syndrome (4 papers, 2009 to 2026). The Ehlers–Danlos syndromes (EDS) are a clinically and genetically heterogeneous group of heritable connective tissue disorders (HCTDs) characterized by joint hypermobility, skin hyperextensibility, and tissue fragility. "Co-occurring CYP21A2 and TNXB variants cause CAH-X syndrome, presenting with combined 21OHD and Ehlers-Danlos syndrome (EDS) features (~10% of 21OHD cases)." (PMID 41180189, 2025).
Hypertension (4 papers, 2009 to 2023). The presence of chronic increased pressure in the systemic arterial system. "In our study, we investigated the associations between rs4409766, rs1004467, and rs3824755 in CYP17A1 and rs2021783 in CYP21A2 and PE; several GWAS had identified these as the genetic variants associated with hypertension in China." (PMID 32977860, 2020). "Several genome-wide association studies have identified single-nucleotide polymorphisms (SNPs), such as rs4409766, rs1004467, and rs3824755 in CYP17A1 and rs2021783 in CYP21A2, as new hypertension susceptibility genetic variants in the Chinese population." (PMID 32977860, 2020). "CYP21A2 encodes 21-hydroxylase enzyme, and mutations in this gene may lead to congenital adrenal hyperplasia, which is characterized by hypertension, hypokalemia, and sexual infantilism." (PMID 32977860, 2020). "The other two genetic loci of CYP21A2 rs2021783 and CYP17A1 rs4409766 were only found to be associated with blood pressure in a Chinese population, which indicated that these SNPs were genetic marker variants of hypertension in Chinese populations." (PMID 32977860, 2020).
Infertility (4 papers, 2011 to 2024). "The detailed pathogenic mechanism of variants associated with CYP21A2 needs to be explored in males, whereas in females it is reported to cause infertility." (PMID 39830005, 2024). "The deficiency of 21-hydroxylase due to CYP21A2 pathogenic variants is a rather frequent disease with serious consequences, going from a real mortality risk to infertility and to milder symptoms, nevertheless important for affecting the patients' self-esteem." (PMID 31333583, 2019). "We found variants in genes categorized into isolated infertility (AR and CFTR), reproductive disorders (SRD5A2), and endocrine disorders (LHCGR and CYP21A2)." (PMID 39830005, 2024).
depression (3 papers, 2021 to 2024). "In this study, we investigated the relationships between CYP21A2 genetic variants and depression in a large cohort of older adults while taking into account multiple causes of depression, including vascular factors and neuropsychiatric comorbidity." (PMID 34034803, 2021). "Variants of the CYP21A2 gene appear as susceptibility factors for late-life depression in a sex-specific manner, independently of somatic and neuropsychiatric comorbidity." (PMID 34034803, 2021). "This study investigated possible associations between five variants in the CYP21A2 gene and late-life depression in 1007 older community-dwelling men and women." (PMID 34034803, 2021). "However, we conducted a cross-analysis of potential sites associated with depression and schizophrenia, which revealed four intersecting sites: BTN3A1, CYP21A2, PSMB4, and TIMP4." (PMID 38637810, 2024). "Variants in the CYP21A2 gene could influence risk of late-life depression, but this has not been examined." (PMID 34034803, 2021). "In previous GWAS and clinical studies, these genes have been associated with neurogenesis (WNT3), neurodevelopmental delays (QRICH1), addiction (HCG27), depression (CCDC71, CYP21A2), and other brain-related disorders." (PMID 39269986, 2024).
Obesity (3 papers, 2017 to 2026). Accumulation of substantial excess body fat. "The most frequently reported gene defect was CYP21A2, while the most commonly reported symptoms/signs were ambiguous genitalia and obesity." (PMID 37347111, 2023).
adrenal incidentaloma (2 papers, 2014 to 2018). "The relationships of CYP21A2 intron 2 polymorphisms and haplotypes with diverse baseline and stimulated blood hormone levels were studied in 106 subjects with non-functioning adrenal incidentaloma (NFAI)." (PMID 25210767, 2014). "Relationship between hormone levels in blood and CYP21A2 haplotype carrier groups in subjects with non-functioning adrenal incidentaloma." (PMID 25210767, 2014).
adrenogenital syndrome (2 papers, 2014 to 2025). Abnormal sex differentiation or congenital disorders of sex development caused by abnormal levels of steroid hormones expressed by the gonads or the adrenal glands, such as in congenital adrenal hyperplasia and adrenal cortex neoplasms. "Eighteen 46,XX female patients with suspected adrenogenital syndrome derived from 21-hydroxylase enzyme deficiency were analyzed for CYP21A2 gene mutations." (PMID 25248670, 2014). "Genetic analysis of CYP21A2 performed in patients with a definitive or presumptive clinical diagnosis of adrenogenital syndrome allowed the identification of the molecular defect in 14 out of 18 (78%) cases." (PMID 25248670, 2014). "The remaining three out of 18 CYP21A2-negative patients, in whom adrenogenital syndrome was suspected, showed regression of clitoral hypertrophy throughout the late neonatal period." (PMID 25248670, 2014).
autoimmune disease (2 papers, 2021 to 2023). A disorder resulting from loss of function or tissue destruction of an organ or multiple organs, arising from humoral or cellular immune responses of the individual to their own tissue constituents. "CYP21A2, as well as MSH5, PPP1R18, and NEU1 have been demonstrated by previous GWASs associated with other autoimmune disorders such as RA, ankylosing spondylitis (AS), T1DM, and SLE." (PMID 37197658, 2023). "Using our refined iTRA approach, we noticed that genes that have far fewer splice junctions in murine mTEC included those encoding homologs of known autoantibody targets in human autoimmune disease (such as PLP1, MBP, and CYP21A2)." (PMID 34649931, 2021).
breast carcinoma (2 papers, 2025).
Hyponatremia (2 papers, 2020 to 2025). An abnormally decreased sodium concentration in the blood. "Patients (six males) with large deletions or conversions of CYP21A2 showed severe clinical manifestations including hyperpigmentation, vomiting, hypotension, hyponatremia, hyperkalemia, and shock, with a high level of 17-OHP." (PMID 33552137, 2020).
pneumonia (2 papers, 2023 to 2025). An acute, acute and chronic, or chronic inflammation focally or diffusely affecting the lung parenchyma, caused by an infection in one or both of the lungs (by bacteria, viruses, fungi, or mycoplasma.). "Similarly, high frequency of MEFV variants in Middle Easterners and Ashkenazi Jews have been proposed to protect against Yersinia pestis infections, CFTR and GJB2 variants against diarrhea, and CYP21A2 variants have been hypothesized to decrease mortality from pneumonia." (PMID 40162233, 2025).
prostate carcinoma (2 papers, 2019 to 2020). A carcinoma that arises from epithelial cells of the prostate gland. "The anti-prostate cancer drug abiraterone inhibited CYP21A2 activity." (PMID 31533365, 2019). "Genes involved in steroid synthesis included CYP21A2, HSD17B2, ITGA6, IDI2, MAP2K1, PMVK, TSPO, and may correspond to androgen dependent growth of prostate cancer." (PMID 32226005, 2020).
adrenal crisis (1 paper, 2018). "Prompt screening in combination with CYP21A2 genetic analyses, enables clinicians to manage severe cases in the neonatal period promptly, even before the appearance of any electrolyte imbalance and/or urgent adrenal crisis." (PMID 30559721, 2018).
Adrenal Hyperandrogenism (1 paper, 2021). Excessive secretion of the androgen hormones dehydroepiandrosterone (DHEA), DHEA sulfate, and androstenedione, from the adrenal gland. "For example, studies investigating the combination of CYP21A2 gene variations together with the G972R variant of the insulin receptor substrate-1 gene, which is more common in PCOS patients with severe adrenal hyperandrogenism, have shown interesting results." (PMID 34071512, 2021).
atherosclerosis (1 paper, 2024). A disease characterized by the build-up of fatty material and calcium deposition in the arterial wall resulting in partial or complete occlusion of the arterial lumen. "As for CYP21A2 gene, there was no relevant literature reported the association between CYP21A2 and atherosclerosis or DM-PAD." (PMID 39649955, 2024).
autism (1 paper, 2008). Persistent deficits in social interaction and communication and interaction as well as a markedly restricted repertoire of activity and interest as well as repetitive patterns of behavior. "Although the combined autism and control study subjects had 50 C4B null alleles only 15 CYP21A2 mutations were detected in over 2250 genotypes." (PMID 18179706, 2008). "The frequency of CYP21A2 mutations was similar between the autism and control groups." (PMID 18179706, 2008). "Therefore, the aim of the present research was to determine if the C4B null allele, found frequently in subjects with autism, is associated with CYP21A2 mutations." (PMID 18179706, 2008). "The frequency of CYP21A2 mutations was similar between the autism and control samples." (PMID 18179706, 2008). "However, a role for CYP21A2 in autism cannot be ruled out as other factors affecting CYP21A2 gene expression such as promoter polymorphisms or epigenetic variation were not studied and may be relevant." (PMID 18179706, 2008). "Therefore, the CYP21A2 mutations studied do not appear to contribute to the etiology of autism." (PMID 18179706, 2008).
autosomal dominant congenital cataracts (1 paper, 2023). "Recently several pathogenic variants of CYP21A2 have been linked to autosomal dominant congenital cataracts, and earlier CYP21A2 was detected in cultures of human lens epithelial cells." (PMID 36914277, 2023).
celiac disease (1 paper, 2024). An autoimmune genetic disorder with an unknown pattern of inheritance that primarily affects the digestive tract. "Our patient received CYP21A2 gene deletion from both of the parents and he also had genetic susceptibilities to T1DM and celiac disease." (PMID 39091607, 2024).
corticotroph adenomas (1 paper, 2025). "The CYP21A2 transcript and protein were absent in both corticotroph tumors from the index case whereas the protein expression was demonstrated in a series of 9 corticotroph adenomas." (PMID 40386408, 2025).
deficiency (1 paper, 2018). "A complete absence of CYP21A2 activity results in glucocorticoid and mineralocorticoid deficiencies as well as androgen excess (virilization)." (PMID 30208164, 2018). "P450-oxidoreductase deficiency combines features of CYP21A2, CYP17A1 and CYP19A1, which are associated with different degrees of severity." (PMID 30208164, 2018).
epilepsy (1 paper, 2024). A brain disorder characterized by episodes of abnormally increased neuronal discharge resulting in transient episodes of sensory or motor neurological dysfunction, or psychic dysfunction. "The study identified three anti-glucose drug target genes, ETFDH, CYP21A2 and CYP2D6, associated with epilepsy." (PMID 38167102, 2024). "It was discovered that three antidiabetic drug target genes, ETFDH, CYP21A2 and CYP2D6, were involved in the occurrence of epilepsy." (PMID 38167102, 2024).
esophageal cancer (1 paper, 2019). A primary or metastatic malignant neoplasm involving the esophagus. "The function of CYP21A2 in esophageal cancer requires further investigation, including in vitro and in vivo experiments." (PMID 30833958, 2019).
esophageal squamous cell carcinoma (1 paper, 2019). Esophageal squamous cell carcinoma (ESCC) is a type of esophageal carcinoma (EC) that can affect any part of the esophagus, but is usually located in the upper or middle third. "CYP21A2 (21-hydroxylase) is a steroidogenic enzyme crucial for the synthesis of mineralocorticoids and glucocorticoids, and was identified as the most frequently mutated gene in esophageal squamous cell carcinoma by whole exome sequencing." (PMID 31921684, 2019).
glucocorticoid deficiency (1 paper, 2017). "However, overall Cyp21a2-deficient mutants showed some residual ability to synthesize cortisol and on a systemic level were less glucocorticoid deficient than our model of glucocorticoid deficiency caused by disruption of the mitochondrial redox cofactor to steroidogenesis ferredoxin 1b (fdx1b)." (PMID 28938470, 2017).
intrauterine growth restriction (1 paper, 2026). "In cases of patients with CAH due to homozygous CYP21A2 variants, suspicion for UPD may be increased if the child also presents with intrauterine growth restriction (IUGR), or transient neonatal diabetes (TNDM) mellitus, associated with maternal and paternal UPD of chromosome 6, respectively." (PMID 42256322, 2026).